IFNG (interferon gamma)
Diseases named in the same sentence as IFNG in open-access papers (continued):
Sharing a sentence is not in itself a finding about the gene and the disease.
tumor (continued). "CD4+ T-cell-derived IFNγ could increase microglial MHCII expression, as observed in our analysis, and then promote microglial phagocytosis of GBM tumor, in a way resembling the report of anti-CTLA-4 treatment." (PMID 39885128, 2025). "Moreover, IFNG emerges as a potential prognostic biomarker and therapeutic target in LUAD, exerting dual effects on tumor microenvironment modulation and tumor angiogenesis." (PMID 39945555, 2025). "In addition, the activated T‐cells produce IFNγ, which diffuses and in mouse models has been shown to induce IFNγ receptor signaling in TAA− bystander tumor cells in distant areas." (PMID 40178291, 2025). "The IFNγ pathways shared the downstream IRF1 and STAT1 molecules that bound with the promoters of PD-L1 and CXCL10, enhancing the efficacy of anti-PD1/PD-L1 inhibitors and boosting T-cell infiltration in the tumor microenvironment." (PMID 40149259, 2025). "This elevated level of tyrosine-phosphorylated STAT1-ΔN did not further increase upon stimulation of isolated tumor cells with either interferon-γ (IFNγ), lipopolysaccharide (LPS), or the combination of both." (PMID 40287766, 2025). "This study further elucidates that anti-PD-L1 immunotherapy induces the release of TNFs and interferon-gamma (IFN-γ) by CD8+ T cells, thereby inhibiting the expression of Xc-system, promoting ferroptosis in tumor cells, and highlighting the pivotal role of ferroptosis in immune therapy." (PMID 39827195, 2025). "B lymphocytes act via interferon-gamma and tumor necrosis factor-alpha to control cancer progression, while natural killer cells participate in tumor defense by attacking cancer cells without antigen activation." (PMID 40016853, 2025). "Moreover, IFNγ released by CD8+ T cells can down-regulate SCL3A2 and SLC7A11 in tumor cells, and promote ferroptosis." (PMID 40959280, 2025). "Indeed, NR4A2/A1R engineered CAR T cells exhibited significantly increased expression of IFNγ, TNF and IL-2 secretion, primarily in CD8+ CAR T cells, following tumor cell coculture." (PMID 40610421, 2025). "This suggested that the strategic positioning of IFNγ-producing CD8+ T cells either supported monocyte recruitment, and/or allowed for monocytes to receive differentiation signals as soon as they entered tumours." (PMID 39746898, 2025). "While LDH release and cytokine secretion were donor‐dependently induced, CD8+ T cells were activated in tumor‐border slices of most donors as denoted by a significant upregulation of CD137 (mean: 2.7% to 3.7%), CD107a (mean: 9.8% to 12.9%) and intracellular IFNγ (mean: 33.1% to 38.4%) expression." (PMID 40952312, 2025). "In the field of tumor therapy, Escherichia coli-derived bEVs have been shown to target and accumulate in tumor tissues, inducing the production of the anti-tumor cytokine CXCL10 and interferon-gamma (IFN-γ) and exerting their anti-tumor effects in an IFN-γ-dependent manner." (PMID 40308573, 2025). "To investigate whether tumours themselves might drive changes in the microenvironment, we treated WT B16-OVA with IFNγ for the indicated period and assessed the expression of a panel of cytokines, for which only CXCL10 was found to be induced by IFNγ." (PMID 39746898, 2025). "Moreover, it led to a rise in the production of effector cytokines TNFα and IFNγ, while simultaneously reducing the levels of immunosuppressive cytokines IL6 and IL10 in tumor tissues." (PMID 40332725, 2025). "Additionally, interferon-gamma controls CD8+ cell function, which is crucial for tumor growth control, inducing malignant cell apoptosis." (PMID 41157229, 2025). "Research shows that these engineered macrophages produce a range of pro-inflammatory cytokines, such as interferon-gamma (IFN-γ), tumor necrosis factor-alpha (TNF-α), and interleukin-12 (IL-12), which are essential for generating a strong anti-tumor immune response." (PMID 40308592, 2025).
tumor (continued). "Flow cytometry analysis revealed an increase in the proliferative (Ki67+), activated (CD69+), and cytotoxic (TNFα+, IFNγ+, GzmB+) CD8+ and CD4+ T cells in tumor tissues and spleens of GL261 tumor-bearing mice treated with cinobufagin, compared to the vehicle-treated group." (PMID 39901195, 2025). "Furthermore, effective enhancement of anti-tumor immunity upon blockade of both LAG-3 and PD-1 requires autocrine interferon-gamma (IFN-γ) signaling." (PMID 41221298, 2025). "IFNG, functioning as an immune response marker, is not directly involved in tumor mutagenesis but rather a consequence of the immune response triggered by mutations." (PMID 40744688, 2025). "Surprisingly, co-culturing PBMCs with tumor cells treated with BET/JQ1, in combination with STING pathway inhibitors (H151, SN011 and C-170) and irradiation, significantly and paradoxically boosted the production of IFNγ." (PMID 40552293, 2025). "The hallmark cytokines of Th1 cells, including interferon-gamma (IFN-γ) and tumor necrosis factor-alpha (TNF-α), facilitate macrophage activation, upregulate major histocompatibility complex (MHC) expression on tumor cells, and potentiate CTL-mediated cytotoxicity." (PMID 40860882, 2025). "IFNG derived from T cells has been reported to predict the efficacy of immune checkpoint inhibitors (ICIs); however, the role of IFNG within tumor cells has not yet been documented." (PMID 39945555, 2025). "However, immune factors, such as IFNγ, is required for IAP inhibitors to achieve their potent anti-tumor effect." (PMID 40057483, 2025). "Similarly, the expression levels of CD25, CD69, and effector molecules IFNγ and GZMB were significantly increased in T cells co‐cultured with I3A‐treated B16‐OVA tumor cells." (PMID 40583248, 2025). "We observed a slight but consistent preferential killing of WT over IFNγRKO tumour cells by OTI CD8+ T cells, consistent with the increase of MHC-I observed in the WT but not IFNγRKO tumour cells following IFNγ treatment." (PMID 39746898, 2025). "The composition is expected to initiate immunogenic cell death (ICD) of tumor cells upon exposure to NIR light, stimulate cytotoxic T lymphocytes (CTLs) that secrete cytokines such as Interferon Gamma (IFN‐γ), and restore the attachment of phospholipids to Acyl‐CoA Synthetase Long Chain 4 (ACSL4)." (PMID 40391083, 2025). "The elevated tyrosine phosphorylation levels did not further increase following IFNγ and/or LPS stimulation of isolated tumor cells." (PMID 40287766, 2025). "In tumor cells, CDK5 expression is crucial for IFNγ-induced CD274 expression." (PMID 41041338, 2025). "The increase in IFNγ positive T cells suggests that, although the total number of immune cells within the tumor did not fluctuate significantly, the functional state of these cells—particularly their ability to produce IFNγ was enhanced." (PMID 40386779, 2025). "Analysis of tissue sections based on hematoxylin and eosin (H&E) staining showed that major organs of mice were not damaged by the long-acting effect of Nano-IFNγ/Zole at the tumor site." (PMID 39776793, 2025). "Lower levels of CXCL12 as a result of IFNγ signalling could therefore significantly re‐shape the TME of NSCLC and influence the localisation of T cells within NSCLC tumours." (PMID 39743376, 2025). "IFNγ blockade resulted in increased frequency of CD45−CD31high tumor endothelial cells but did not alter the frequencies of MECA-79+ TA-HECs and bifunctional MECA-79+CD62P+ TA-HECs." (PMID 40460830, 2025). "Recent studies indicate that the interplay of specific cytokines, including TNF and interferon-gamma (IFN-γ), might trigger PANoptosis in neoplastic cells, potentially resulting in decreased tumor size in preclinical models." (PMID 40422233, 2025). "Indeed, looking at the most variable genes in the immune compartment of the TME before and after ACT, a core IFNγ response gene set (for example, Cxcl9, Gbp2 and Slamf7) was strongly increased in NTT tumours." (PMID 39604727, 2025).
tumor (continued). "In addition, the itaconate derivatives-treated tumor cells also increased the intracellular GZMB and IFNγ expression, and CD25 expression on T cells in the tumor-T cell co-culture system." (PMID 39349845, 2024). "To understand the tumor-cell intrinsic effects of EZH2 inhibition, we treated four different NSCLC cell lines with the EZH2 inhibitors GSK126 or EPZ6438 for 5 days, followed by 2 days of EZH2 inhibition with IFNγ." (PMID 38265267, 2024). "In many studies, increases in iNKT cell numbers and IFNγ levels were observed but unfortunately, unlike many pre-clinical mouse studies, limited anti-tumor efficacy was seen and ranged from no response up to a partial response (PR)." (PMID 39170618, 2024). "Moreover, qRT-PCR results revealed significant upregulation of CD27, CXCL13, IFNG and GZMB in tumor-specific T cells using." (PMID 39033098, 2024). "Treatment of tumor-bearing animals with OX40/CD137 bispecific agonists reprograms Tregs into both fragile Foxp3+ IFNγ+ Tregs with decreased suppressive function and lineage-instable Foxp3− IFNγ+ ex-Tregs." (PMID 38995700, 2024). "We also observed a significant increase in the infiltration of total CD8+ T cells, IFNγ+ CD8+ T cells, and perforin+ CD8+ T cells within the TME, suggesting that cryoablation restored the cytotoxic ability of CD8+ T cells against tumor cells." (PMID 39648199, 2024). "Consistently, we detected significantly increased infiltration and activation of CD8+ T cells in the shTrp63 group compared with the Scramble group in HNM007 tumor samples, as measured by the levels of activation and cytotoxic protein markers (CD69, GZMB, IFNγ) using flow cytometry analysis." (PMID 38509096, 2024). "Recent investigations have demonstrated that Interferon-gamma (IFNγ) promotes the expression of ACSL4, leading to alterations in lipid profiles within tumor cells, consequently increasing the presence of arachidonic acid (AA) in phospholipids containing C16 and C18 acyl chains." (PMID 39420203, 2024). "Interestingly, PRMT3-OE led to a small but significant increase in the tumor volumes and weights and a decrease in T cell infiltration (CD4+, CD8+, and IFNγ+ and GZMB+ CD8+ T cells) in HSP60-R446K OE cells compared to vector control." (PMID 39256398, 2024). "IFNγ enhances ferroptosis under erastin or RSL3 treatment by promoting STAT1 binding to the SLC7A11 promoter, depleting GSH, and increasing lipid peroxidation in tumor cells." (PMID 39595619, 2024). "Exposure of tumor cells to IFN-I and IFNγ may have an immunosuppressive effect, mediated by PD-L1 and LGALS9." (PMID 38672681, 2024). "Furthermore, mLama4-specific CD8+ TILs from T3-HDVax-treated mice expressed high levels of exhaustion markers (PD1, CD39, TIM3, LAG3 and TOX) and produced low amounts of IFNγ and TNF compared with similar populations from T3-LDVax-treated tumour-bearing mice." (PMID 39048822, 2024). "Furthermore, GSEA analysis showed reductions in genes related to anti-tumor immune responses including the IL-2/STAT5 pathway, the interferon-gamma response and the PI3K/AKT/mTOR signaling." (PMID 38659818, 2024). "In the early stages of tumorigenesis, M1 macrophages maintain themselves by secreting large amounts of the pro-inflammatory cytokines IFNγ and IL12, which demonstrate anti-tumor activity, and induce the infiltration and activation of cytotoxic T-cells at the tumor site." (PMID 39065562, 2024). "The expression of activation-specific genes (IFNG, GZMB, and TNFRSF9) and cell proliferation-specific genes (IL2, IL2RA, and CD28) decreased with the increasing rounds of tumor stimulation, especially from round 2 (the round in which tumor-killing ability begins to decline)." (PMID 39657666, 2024).
tumor (continued). "Collectively, these findings indicate that B16F10 tumor response to DCP-IL-12/FLT3L is strictly IFNγ-dependent, involves a diverse assortment of IFNγ-producing cells and may depend, at least in part, on the antitumoral activity of IFNγ-stimulated M1-like TAMs." (PMID 37996514, 2024). "While this sub-cohort exhibited a significant increase in IFNg release post Nivolumab treatment, tumor cytotoxicity was not as high as in SC1." (PMID 38383563, 2024). "Additionally, abrogation of endothelial Notch unleashed interferon gamma responses in the tumor microenvironment, upregulated PDL1 expression on tumor cells, and sensitized PDAC to PD1-based immunotherapy." (PMID 38947054, 2024). "While mice treated with a combination of IFNγ/α and anti-PD1 display a marginal reduction in tumor growth, it is not significant and no change in the levels of activated CD8+ T cells was observed in either the blood or the tumor." (PMID 38181798, 2024). "Previous studies reported that upregulation of IFN-γ (gene name, IFNG) and 41BB (gene name, TNFRSF9) expression on activated T cells could be applied to recognize and isolate tumour-specific T cells." (PMID 38727812, 2024). "The results of the P815-IFNG tumor models displayed a significant increase in the transcriptional or translational levels of murine IFNG and CXCL10 in the light group, rather than IL-6 or IL-10." (PMID 39080467, 2024). "To explore these inquiries, we analyzed public databases to compare the levels of CD137 highly (CD137hi) expressing-IFNγ-producing CD8+ T cells, IL12-producing M1 cells and CCL17-producing M2 in tumor tissues from five different cancer types, depending on the response to anti-PD-1 treatment." (PMID 38254759, 2024). "To mimic IFN conditions in the tumor microenvironment (TME), we added IFNγ exogenously in SCC cells since (i) IFNγ pathway is the most significant pathway negatively regulated by TP63, (ii) IFNγ receptors (IFNGR1, IFNGR2) have higher expression than IFNα receptors (IFNAR1, IFNAR2) in SCC cells." (PMID 38509096, 2024). "Within the tumor, markers of immunogenic cell death [calreticulin and high-mobility group box 1 protein (HMGB1)] were increased, and the serum proinflammatory cytokines IL-6, TNFα, and IFNγ also were upregulated, as compared to other treatment groups." (PMID 38803496, 2024). "Activated T-cells secrete type-II IFN (IFNγ) and enhance MHC-I expression on tumor cells." (PMID 39518094, 2024). "A study revealed that IFNγ derived from immunotherapy-activated CD8+ T cells act synergistically with radiotherapy to inhibit SLC7A11 which results in reduced cystine uptake, and increased tumor lipid oxidation and ferroptosis, thereby tumor suppression." (PMID 38705513, 2024). "We isolated tumor infiltrated CD8 cells and stimulated with anti-CD3/anti-CD28 Abs ex vivo only for a short period of time to stimulate only those cells that were actively producing IFNγ in vivo." (PMID 38789421, 2024). "89Zr-anti-IFNγ, developed by Gibson, can be used to assess IFN-γ levels and may be potentially used as a probe for assessing active anti-tumor T cell activity and predicting treatment outcomes in animal models." (PMID 39072335, 2024). "It is worth noting that immune exclusion, which causes resistance to ICB, can result in a different metabolic tumor microenvironment due to reduced levels of infiltrating CD8+ T cells and IFNγ gene signature, which also impact the outcome of metabolic innervation." (PMID 38216787, 2024). "In mouse tumor model, the frequency of MDSCs inversely correlates with the expression of NK cell-activating receptors including NKG2D and natural cytotoxicity triggering receptor 3 on the NK cell surface, as well as with IFNγ and PRF1 (perforin 1) production." (PMID 39229258, 2024). "Importantly, anti-IL-33 monoclonal antibody therapy increase the percentage of CD4+IFNγ+ T cells and decreased CD4+ and CD8+ T cells secreting IL-4 in tumour-draining lymph nodes." (PMID 38662248, 2024).
tumor (continued). "IFNγ could induce the expression of IFITM3 and STAT1, and the IFITM3 cKO mice showed higher IFNγ expression in the tumor environment to mediate a more robust anti-tumor response." (PMID 38167862, 2024). "In the liver sample of patient 3, a low IFNγ score was seen, which can probably not fully be contributed to the tumor itself but can partly be explained by the liver microenvironment." (PMID 38280045, 2024). "Notably, hYP218 CAR T cells were maintained in an activated state in the tumour microenvironment, indicated by the expression of CD39 and CD69 markers along with increased IFNγ, and TNFα secretion." (PMID 39548594, 2024). "Additionally, AR suppresses the activity and stemness of male tumor-infiltrating CD8+ T cells by modulating epigenetic and transcriptional programs, such as androgen-driven IFNγ repression." (PMID 39682229, 2024). "IFNγ induces macrophages to produce more CXCL9 and CXCL10, two chemokines that bind to CXCR3 on the surface of T cells and promote their recruitment for anti-tumor immune response." (PMID 38787372, 2024). "Interestingly, restoration of the OST complex complemented N-glycosylation that restored the IFNγ production and alleviated CD8+ T cell exhaustion, consequently resulting in reduced tumor growth in preclinical models." (PMID 38881904, 2024). "Control TILs and attIL12-T cells, in which IFNγ induction is activated by a single signal, resulted in delayed tumor development compared to no treatment." (PMID 39574893, 2024). "Despite contrasting therapeutic mechanisms between ICK and IL‐2‐Fc and small differences between mouse tumor models, in each instance ICK and IL‐2‐Fc treatments resulted in similar tumor growth inhibition due in large part to increased IFNγ+CD8+ T cells and/or decreased Tregs in the tumor." (PMID 38317590, 2024). "T127 tumor cells treated in vitro with AZD5305 and then cocultured in a transwell system with C5aR1 macrophages resulted in C5aR1 macrophages that suppressed T cell activation as assessed by positivity for GMZB, PRF1 or IFNγ." (PMID 38802355, 2024). "Therefore, the experimental results of this part further prove that Bacteroides fragilis can restore the combined anti-tumor effect of Ad-E and αPD-1 through the accumulation of CD3+ T cells, NK cells, IFNγ+CD8+ T cells to a certain extent." (PMID 39251538, 2024). "SCC tissue and proximal healthy tissue also showed different responses to direct CP ex vivo, with higher levels of cytochrome c, higher IL10, TNFα, and IFNγ release, and lower IL22 released from tumour tissue indicating significantly increased stress and apoptosis in malignant tissues." (PMID 38785562, 2024). "Moreover, the administration of arachidonic acid, an omega-6 PUFA, combined with interferon gamma (IFN‐γ), mediated ferroptosis in tumor cells in an acyl-coenzyme A synthetase long-chain family member 4 (ACSL4)-dependent manner." (PMID 38641847, 2024). "Although expression of IFNγ by tumour-specific CD8+ T-cells in the tumour was not altered, direct IFNγ neutralization during IAV infection of tumour-bearing mice abolished the positive effect." (PMID 38271469, 2024). "However, our understanding of the complex nature of inflammatory cytokines within the tumor microenvironment (TME) remains perplexing, especially for pleiotropic nature of cytokines such as IL-12 and IFNγ." (PMID 38786066, 2024). "B lymphocytes control cancer progression through cytokines like interferon-gamma and tumor necrosis factor-alpha while natural killer cells directly attach malignant tumor cells without the need for antigen activation." (PMID 39396135, 2024). "We found that IL12, IL27, and IFNγ, which could increase the STAT1 expression to induce Th1 response in the tumor microenvironment, could also induce high expression of IFITM3 of Treg cells." (PMID 38167862, 2024).